TMC4 (transmembrane channel like 4)
Description:
Voltage-gated chloride channel involved in high-concentration salt taste sensation. Depolarization induced by high NaCl concentration may trigger the activation of TMC4-mediated chloride influx into taste bud cells, helping the return to resting potential. Also allows permeation of organic anions including gluconate, but their current amplitudes at positive potentials are less than that of chloride. Involved in pH and temperature-dependent modulation of salty taste.
Gene: Protein-coding gene on chromosome 19 (54,160,095 to 54,173,250, reverse strand). Ensembl gene ENSG00000167608.
Subcellular location: Membrane
Subcellular location (Human Protein Atlas): Vesicles
Genetic constraint (gnomAD): Loss-of-function variants: 69 observed, 80.17 expected, observed/expected ratio (o/e) 0.86, 90% interval 0.71 to 1.05. The upper end of that interval is the gene's LOEUF score, 1.05, which puts it in group 4 of 6, group 1 being the genes least tolerant of losing a copy. Missense variants: 858 observed, 867.03 expected, observed/expected ratio (o/e) 0.99, 90% interval 0.94 to 1.05. Synonymous variants: 434 observed, 391.47 expected, observed/expected ratio (o/e) 1.11, 90% interval 1.02 to 1.2.
Homologues: Orthologues: chimpanzee TMC4 (99% identical), macaque TMC4 (94% identical), dog TMC4 (83% identical), pig TMC4 (82% identical), guinea pig TMC4 (77% identical), rat Tmc4 (76% identical), mouse Tmc4 (75% identical), tropical clawed frog tmc4 (40% identical), zebrafish tmc4 (37% identical), Caenorhabditis elegans tmc-2 (21% identical), Caenorhabditis elegans tmc-1 (20% identical). Paralogues in human: TMC7 (36% identical), TMC8 (32% identical), TMC3 (23% identical), TMC5 (23% identical), TMC6 (22% identical), TMC2 (21% identical), TMC1 (20% identical).
Diseases named in the same sentence as TMC4 in open-access papers:
TMC4 is named in the same sentence as 14 diseases in open-access papers, as found by Europe PMC text mining. Sharing a sentence is not in itself a finding about the gene and the disease. The quoted sentences say what the papers report.
Hepatic steatosis (5 papers, 2019 to 2025). Steatosis is a term used to denote lipid accumulation within hepatocytes. "In contrast to the striking hepatic steatosis seen with Mboat7 loss of function, Tmc4 null mice show similar levels of hepatic lipids when fed a high fat diet." (PMID 31621579, 2019). "To understand the role of Tmc4 in hepatic steatosis, we generated global Tmc4 knockout mice using CRISPR-Cas9-mediated gene editing and examined hepatic lipid levels under high fat feeding conditions." (PMID 31621579, 2019). "Given the fact that the rs641738 polymorphism is located in exon 1 of the TMC4 gene, and we unexpectedly found that Mboat7 ASO treatment also reduces Tmc4 expression, we wanted to examine whether alteration in Tmc4 may also be a key regulator of hepatic steatosis." (PMID 31621579, 2019). "We previously showed that mice lacking Tmc4 (Tmc4−/−) have normal high fat diet-induced hepatic steatosis." (PMID 38648183, 2024). "Despite the proximity of the SNPs to TMC4, it is unlikely that TMC4 directly causes NAFLD because this gene is expressed at very low levels in liver, and Tmc4 KO mice do not exhibit fatty liver." (PMID 32859645, 2021). "Although the rs641738 polymorphisms maps to the first exon of the poorly annotated gene TMC4, this study is the first to demonstrate that genetic deletion of Tmc4 does not result in hepatic steatosis." (PMID 31621579, 2019). "However, genetic deletion of Tmc4 did not provoke hepatic steatosis, which is an important finding because the human rs641738 SNP lies within exon 1 of the TMC4 gene." (PMID 35636492, 2022).
liver disease (3 papers, 2019 to 2021). "A hot genetic variant, rs641738 within the membrane-bound O-acyltransferase domain containing 7(MBOAT7) and transmembrane channel-like 4 (TMC4), was recently reported to be associated with several liver diseases." (PMID 34113561, 2021). "Within the last two years, several independent GWAS studies have identified a liver disease susceptibility locus (rs641738) within a linkage-disequilibrium block that contains genes encoding MBOAT7 and TMC4." (PMID 31621579, 2019). "first reported that genetic deletion of Tmc4 in mice may not lead to hepatic steatosis, but the loss of function of its neighboring gene Mboat7 could result in liver disease progression in mice." (PMID 34113561, 2021). "Furthermore, we show that Mboat7, but not Tmc4, loss of function in mice is sufficient to drive NAFLD progression, and show that Mboat7 substrate lipids (LPIs) may be critical mediators of obesity-linked liver disease progression." (PMID 31621579, 2019).
liver fibrosis (3 papers, 2019 to 2022). "In addition, the rs641738 C > T variant, near two genes encoding membrane-bound O-acyltransferase domain-containing 7 (MBOAT7) and transmembrane channel-like 4 (TMC4), was shown to be associated with the progression of NAFLD and liver fibrosis." (PMID 34359642, 2021).
breast carcinoma (2 papers, 2020 to 2023). "TMC4 can be used as a prognostic marker for breast cancer, and its high expression was associated with a better prognosis." (PMID 37468683, 2023).
infections in the skin (1 paper, 2016). "More interesting, we found five genes (CDKN2A, COL8A2, RASSF6, TMC4, and TMC5) from our 145 genes are associated with Walt’s disease (corrected P-value = 0.0040), which are infections in the skin caused by the human papillomavirus (HPV)." (PMID 27830726, 2016).
peritonitis (1 paper, 2021). Inflammation of the peritoneum (tissue that lines the abdominal wall and covers most of the organs in the abdomen). "We used a mouse model of peritonitis to evaluate the inflammatory response profile induced by the nattectin-like toxin TmC4-47.2." (PMID 35050979, 2021).
cancer (2 papers, 2019 to 2021). A tumor composed of atypical neoplastic, often pleomorphic cells that invade other tissues. "For example, TMC6 and TMC8 were highly positively correlated with macrophages, B cells, and T cells in most cancer types, while TMC4, TMC5, and TMC7 were negatively correlated with those cells in diverse cancer types." (PMID 34899684, 2021). "The results showed that TMC4 and TMC5 have a similar expression pattern in different cancers, as do TMC6 and TMC7." (PMID 34899684, 2021). "Further, TMC4, TMC5, TMC6, TMC7, and TMC8 were tissue-specifically and cancer-specifically expressed." (PMID 34899684, 2021).
TMC4 also shares sentences with these, for which no sentence is quoted: steatosis (2 papers); tumor (2); amyloid (1); neurodegenerative disease (1); non-alcoholic fatty liver disease (1); non-alcoholic steatohepatitis (1); viral hepatitis (1).